TLR9 (toll like receptor 9)
Diseases named in the same sentence as TLR9 in open-access papers (continued):
Sharing a sentence is not in itself a finding about the gene and the disease.
pulmonary fibrosis (19 papers, 2011 to 2026). Chronic progressive interstitial lung disorder characterized by the replacement of the lung tissue by connective tissue, leading to progressive dyspnea, respiratory failure, or right heart failure. "Little is known about lung fibrosis during cryptococcal infection, but our results showed that eosinophilia and fibrosis were associated with TLR9-/- absence in the course of C. gattii infection." (PMID 36145419, 2022). "Fibroblast-specific deficiency of TLR4 is protective against fibrosis; however, mice deficient in TLR4, TLR2, and TLR9 exhibited aggravated pulmonary fibrosis." (PMID 36110858, 2022). "Multiple TLRs, including TLR9, have been implicated in the progression of pulmonary fibrosis." (PMID 39964756, 2025). "In our model, we observed hyperplasia of type 2 alveolar epithelial cells (main source of SPD in the lung) in both WT and TLR9-/- infected mice 21 days after C. gattii inoculum, which is associated with a mice model of pulmonary fibrosis and idiopathic pulmonary fibrosis." (PMID 36145419, 2022). "Similarly, TLR9 overexpression is associated with pulmonary fibrosis and is an indicator of fibrosis." (PMID 35765703, 2022). "Similarly, TLR9-mediated IFN-β induction in fibroblasts has shown to be protective against pulmonary fibrosis, and TLR9-deficient mice have exacerbated pulmonary fibrosis." (PMID 34258628, 2021). "Moreover, TLR9 deficient mice have attenuated antiviral responses (by a higher production of IFN-β) limiting its use in the MHV68-induced lung fibrosis model." (PMID 31170232, 2019). "In contrast, deletion of TLR9 exacerbated skin and lung fibrosis and increased inflammatory cell infiltration, suggesting a protective role for TLR9 in this model." (PMID 41614927, 2026). "In a mouse model of SSc disease, the deletion of TLR7 attenuated skin and lung fibrosis, while the deletion of TLR9 exacerbated skin and lung fibrosis." (PMID 38892317, 2024). "TLR9 is highly expressed in patients with rapidly progressive idiopathic pulmonary fibrosis (IPF) and its agonist exacerbates fibrosis in a humanized SCID mouse model of IPF6." (PMID 35864207, 2022). "Our results suggest that TLR9-/- infected mice had intense pulmonary fibrosis, hypereosinophilia and type 2 epithelial alveolar cell hyperplasia." (PMID 36145419, 2022). "Studies in other injury models and investigations in patients with idiopathic pulmonary fibrosis (IPF) suggest a contribution of further TLR such as TLR3, TLR7 or TLR9 in the pathogenesis of pulmonary fibrosis." (PMID 28836991, 2017). "It has been shown that the expression of TLR9 in the lung is positively correlated with the abundance of Staphylococcus and Prevotella, and the interaction between TLR9 and the microbiota is associated with improved progression-free survival (PFS) in pulmonary fibrosis." (PMID 41293166, 2025). "In TLR9 knockdown mice, pulmonary fibrosis was alleviated and cellular pyroptosis was reduced." (PMID 40391214, 2025). "In addition, TLR9-/- mice developed severe pulmonary fibrosis and areas with strongly birefringent fibers." (PMID 36145419, 2022). "We demonstrate that targeting TLR9 or PI3Kγ appear as promising approaches to control sterile organ damage provoked by toxic irritants such as silica-induced lung fibrosis and drug-induced liver injury since these were dependent on TLR9 receptor and PI3Kγ activity." (PMID 31836766, 2019). "In this study, the authors hypothesized that the observed reduction in lung fibrosis in response to CpG-ODN treatment is due to the increased TLR9 induced Interferon-beta (IFN-β) expression, which was shown to reduce lung fibroblast proliferation." (PMID 24478703, 2014). "The role of TLR9 in fibrosis was further studied in vivo using mouse models of lung fibrosis." (PMID 24478703, 2014). "TLR-9 signaling is protective during viral exacerbation of murine pulmonary fibrosis." (PMID 21810214, 2011).
pulmonary fibrosis (continued). "Thus, there are now at least two examples of TLR-9 signaling showing a protective effect in lung-fibrosis models in mice." (PMID 21810214, 2011). "Additionally, ER stress in AECII cells inhibited PINK1-mediated mitophagy, leading to extracellular release of mtDNA, which activated toll-like receptor 9 (TLR9) and triggered transforming growth factor-β (TGF-β) secretion, further increasing susceptibility to pulmonary fibrosis." (PMID 39183973, 2024). "Based on the result that a “TLR9 deletion hardly affects the change in the ratio of pDC”, we can conclude that TLR9 may not be a direct or critical factor in increasing the degree of skin and lung fibrosis." (PMID 38892317, 2024). "A high number of eosinophils in pulmonary mixed cellular infiltrate, large interstitial pulmonary fibrosis and type 2 alveolar epithelial cell hyperplasia support the hypothesis that TLR9 plays an important role in controlling the infection at the primary site." (PMID 36145419, 2022). "Thus, the inhibitory effect of MHP1-AcN on TLR9 signaling in fibroblasts might also contribute to the prevention of bleomycin-induced lung fibrosis." (PMID 35864207, 2022). "Considering a recent report that the loss of RAGE contributes to pulmonary fibrosis, the increase of HMGB1 in alveolar fluids itself may induce fibrogenesis through other HMGB1 receptors, such as the Toll-like family of receptors (TLRs), TLR4, TLR2, or TLR9." (PMID 21637372, 2011). "The histological analysis revealed that TLR7-KO mice treated with bleomycin had less lung fibrosis than BLM-treated WT mice, whereas TLR9-KO mice treated with bleomycin had more lung fibrosis than BLM-treated WT mice." (PMID 38892317, 2024). "Mitochondrial DNA unites with TLR9 on alveolar epithelial cells to trigger the expression of TGF and IL-1/6, which leads to increased α-SMA and collagen I synthesis during pulmonary fibrosis." (PMID 36110858, 2022). "Previous studies have demonstrated that mtDNA can trigger inflammatory cytokine production and aggravate lung fibrosis through TLR9 signaling and noncanonical cGAS-STING signaling." (PMID 38790051, 2024). "The evidence suggests that a TLR9 deletion has little effect on the proportion of pDCs, indicating that a TLR9 deletion is not a key factor in increasing the degree of skin and lung fibrosis." (PMID 38892317, 2024). "Although there was no published direct evidence of TLR9 involvement in silicosis, other authors have demonstrated a correlation between TLR9 and pulmonary fibrotic diseases such as idiopathic pulmonary fibrosis or fibrosis induced by paraquat." (PMID 31836766, 2019). "As TLR-9 signaling in human IPF fibroblasts appears to lead to a more profibrotic phenotype, these data highlight important differences between the human and mouse disease, and the limitations of our current animal models of pulmonary fibrosis." (PMID 21810214, 2011).
acute kidney injury (18 papers, 2015 to 2025). Sudden and sustained deterioration of the kidney function characterized by decreased glomerular filtration rate, increased serum creatinine or oliguria. "Extracellular histones can interact with TLR2, TLR4 and TLR9 to cause organ damages in acute kidney injury and sterile inflammatory liver injury." (PMID 32432055, 2020). "Here, using a traditional mouse AKI→CKD transition model, the roles of TLR-9 during the transition from acute kidney injury (AKI) to chronic kidney disease (CKD) were further explored." (PMID 33644078, 2021). "Other experimental studies furthermore show that TLR9 is an important mediator of hepatic injury secondary to ischemic acute kidney injury." (PMID 33519463, 2020). "In contrast, our data indicates that TLR9 is an important mediator of hepatic injury secondary to ischemic acute kidney injury." (PMID 26361210, 2015). "Several studies also have explored the role of TLR9 using experimental acute kidney injury (AKI)." (PMID 36176986, 2022). "Taken together, this study indicated that proper use of HCQ could be a new strategy for anti-fibrotic therapy and that TLR-9 could be a potential therapeutic target for CKD following acute kidney injury." (PMID 33936063, 2021). "A previous report using a model of ischemic acute kidney injury showed that TLR9 activation did not impact renal function following renal ischemia but mediated secondary hepatic injury." (PMID 37662481, 2023). "used PLGA nanoparticles to deliver ODN2088, a TLR9 antagonist, to renal tubular cells in a model of ischemic reperfusion injury (IRI)‐induced acute kidney injury (AKI)." (PMID 40599085, 2025).
HIV-1 infection (18 papers, 2009 to 2025). The type species of lentivirus and the etiologic agent of acquired immunodeficiency syndrome (AIDS). "There is data that the presence of the TLR9 gene SNP rs352140 (1635A/G) with the GA and GG genotypes is associated with increased viral load and an increased risk of HIV-1 infection, but the mechanisms by which TLR9 affects viral load are still unclear." (PMID 41305532, 2025). "Although our epidemiological study suggests a possible association between opiate use and HIV-1 infection in the context of the TLR9 pathway, the molecular mechanisms remain to be further determined." (PMID 29026137, 2017). "In addition, a polymorphism in the TLR9 gene is associated with HIV-1 infection, progression, and vertical transmission." (PMID 32547554, 2020). "Frequencies of TLR9 genotypes and haplotypes and risk of HIV-1 infection." (PMID 20500814, 2010). "Moreover, these TLR9 variants may influence the clinical course of HIV-1 infection, and the development of endometrial cancer, osteoarthritis, and non-Hodgkin lymphoma." (PMID 22714906, 2012). "As an example, agonists for TLR3, TLR7, TLR8, and TLR9 have been shown to be capable of inhibiting HIV-1 infection and induced IFN-α-stimulated gene expression in PBMCs in vitro." (PMID 38994942, 2024). "We have previously shown that TLR9 agonist treatment during HIV-1 infection led to increased activation of pDCs and higher expression of their T cell co-stimulatory markers." (PMID 37664600, 2023). "When TLR3, TLR7, TLR8, and TLR9 agonists were added before HIV-1 infection, they significantly reduced peripheral blood mononuclear cell infection." (PMID 35211115, 2022). "We also investigated the levels of antiviral factors (IFN-α and IFN-β) and CC chemokines (MIP-1α, MIP-1β, and RANTES, the ligands of the HIV entry coreceptor CCR5) related to both the TLR9 pathway and HIV-1 infection/replication." (PMID 32547554, 2020). "Our data reveal that opiate use plays a cofactor role in pathogenesis of HIV-1 infection through inhibition of TLR9 pathway." (PMID 29026137, 2017). "Overall, results demonstrate a significant correlation between specific genetic variants of the TLR9 gene and risk of MTCT of HIV-1, thus confirming a critical role of innate immunity in perinatal HIV-1 infection." (PMID 20500814, 2010). "In conclusion, our results demonstrate an important role of genetic variants of the TLR9 gene in modulating the risk of MTCT of HIV-1, thus confirming the relevance of innate immunity in perinatal HIV-1 infection." (PMID 20500814, 2010). "Prior addition of TLR3, TLR7, TLR8, and TLR9 agonists was shown to inhibit HIV-1 infection in peripheral blood mononuclear cells (PBMCs); TLR8 and TLR9 agonists were found to be more effective in blocking HIV-1 replication, along with the activation of other antiviral sensors." (PMID 37298575, 2023). "We chose to study TLR2 and TLR9 because of the important role they play in HIV-1 infection." (PMID 37513727, 2023). "Interestingly, the addition of TLR8 and TLR9 agonists 48 h and 72 h after HIV-1 infection, respectively, were highly effective in preventing HIV replication." (PMID 35211115, 2022). "Taken together, these in vitro experiments further indicated that opiate use may inhibit the TLR9 signaling pathway, thus playing a key role in pathogenesis of HIV-1 infection." (PMID 29026137, 2017). "To determine whether opiate use and/or HIV-1 infection had an impact on the TLR9 signaling pathway, we examined the expression of TLR9 protein in human PBMCs among the four groups by western blot." (PMID 29026137, 2017). "Unsurprisingly, the expression of TLR9 in the Opiate+ HIV+ group was significant lower than that in the Opiate− HIV+ group in our study, implying that opiate use could enhance this inhibitory effect of HIV-1 infection on the expression of TLR9." (PMID 29026137, 2017). "In conclusion, both TLR7 and TLR9 responses are impaired in HIV-1 infection." (PMID 22470494, 2012).
HIV-1 infection (continued). "However, the upregulated TLR9 may shed light on the understanding of HSV-2 enhanced HIV-1 infection." (PMID 32194565, 2020). "In addition, HIV-1 infection itself may also alter the expression of key factors in the TLR9 signaling pathway and disrupt the TLR9 signaling pathway and subsequent innate responses, which provides a novel mechanism for HIV-1 immune escape." (PMID 29026137, 2017). "This KEGG pathway has been related to enhanced HIV-1 infection and morphine treatment has been shown to promote HIV-1 replication in macrophages via inhibition of the TLR9 pathway." (PMID 32512929, 2020). "In the present study, we continued to examine the expression of TLR9 protein and its downstream factors and explored whether opiate use inhibits the TLR9 signaling pathway and thereby modulates innate immune function, thus facilitating the pathogenesis of HIV-1 infection." (PMID 29026137, 2017). "We found that in B-cells from patients with chronic HIV-1 infection, AID expression was induced in vitro upon CD40-dependent and TLR9 stimulation but less efficiently than in controls where the fold increase was much higher." (PMID 19412542, 2009). "In spite of the reduced circulating IFN-α levels and impaired production upon TLR9 and/or TLR7 stimulation in vitro, there is increasing evidence of increased IFN-α production in vivo during HIV-1 infection." (PMID 19936055, 2009). "To understand how the transcriptome of pDCs is impacted by HIV-1 infection and exogenous stimulation, we isolated pDCs from healthy controls, people with HIV-1 (PWH) before and during toll-like receptor 9 (TLR9) agonist treatment and performed single-cell (sc)-RNA sequencing." (PMID 37664600, 2023). "Thus, some translocated microbial products can directly induce B cells to differentiate into IL-10-producing B cells in untreated HIV-1 infection via TLR-2 and/or TLR-9 signaling pathway." (PMID 24586620, 2014). "Worth noting, we found that in HIV-1 infection the levels of MxA expression directly correlated with viremia and were inversely related to the circulating pDC levels and the amount of IFN-α production upon in vitro TLR9 stimulation." (PMID 19936055, 2009). "At this point, HIV-1 infection resulted in a trend toward suppression of Toll-like receptor 3 (TLR3) protein expression on splenic but not peripheral CD4 T cells, whereas peripheral TLR7 and TLR9 protein expression was elevated after HIV-1 infection of both CD4 T cells and macrophages." (PMID 30867315, 2019). "We also found that HIV-1 infection alone also led to the lower expression of TLR9 whether the HIV-1-infected subjects were opiate users or not, which is in agreement with the reports that TLR9 polymorphisms clinically affect HIV-1 progression." (PMID 29026137, 2017).
pancreatic cancer (17 papers, 2010 to 2024). "In pancreatic cancer, the expression of TLR2 and TLR4 is mainly increased, and is associated with higher mortality,while TLR9 shows a downward trend in pancreatic cancer." (PMID 38110966, 2023). "It has been reported that, in pancreatic cancer, high TLR9 expression is associated with the increase of patient survival up to 15 months." (PMID 34884547, 2021). "TLRs 7 and 9 have been speculated to accelerate tumor progression in pancreatic cancer, but clinical studies have shown TLR9 to be associated with better prognosis." (PMID 31314777, 2019). "Our findings are highly relevant in pancreatic cancer therapy, particularly for TLR9, which cannot be targeted with classical antibodies due to its intracellular expression." (PMID 38390872, 2024). "In this study, we tested, for the first time, an intrabody-mediated TLR blockade in human TLR2- and TLR9-expressing pancreatic cancer cells for its effects on inflammatory signaling-mediated tumor growth." (PMID 38390872, 2024). "In this study, we consequently targeted both TLRs (TLR2 and TLR9) using ER intrabodies in pancreatic cancer cells to prove their inhibitory effects on tumor growth." (PMID 38390872, 2024). "Our results are consistent with findings from other groups showing that blocking TLR4 or TLR9 potentiates pancreatic cancer cells to apoptosis." (PMID 38390872, 2024). "Recently, two intrabodies were selected, blocking TLR2 and TLR9 and inhibiting ex vivo inflammation-mediated pancreatic cancer cell growth." (PMID 39769267, 2024). "TLR9 in pancreatic stellate cells has been shown to increase the proliferation of pancreatic cancer cells via paracrine signaling." (PMID 38390872, 2024). "Recent studies have shown that intratumoral injection of TLR9 agonists enhances the efficacy of anti–PD-1 ICB therapy in mouse models of pancreatic cancer and head and neck squamous cell carcinoma." (PMID 36278484, 2022). "Intratumoral injection of TLR9 agonists enhances the efficacy of anti–PD-1 ICB therapy in mouse models of pancreatic cancer and head and neck squamous cell carcinoma." (PMID 36278484, 2022). "Studies that aim to develop strategies to improve the response rate of ICB therapy have shown that combining TLR9 agonists with anti–PD-1 ICB therapy enhances anti–PD-1 treatment in mouse models of pancreatic cancer and head and neck squamous cell carcinoma." (PMID 36278484, 2022). "On the other hand, the activation of TLR9 is responsible for the fibrotic phenotype of pancreatic stellate cells and for the promotion of epithelial cell proliferation, and this confers to TLR9 a cancer-promoting role in the pancreatic cancer." (PMID 34884547, 2021). "In particular, the stimulation of TLR9 plays an inhibitory role in pancreatic cancer cell proliferation." (PMID 34884547, 2021). "Currently, for pancreatic cancer, combination therapy including TLR9-activating CpGs is being evaluated in two clinical trials (Clinicaltrials.gov accessed on 28 October 2021: # NCT04612530 and # NCT04050085)." (PMID 34884547, 2021). "In RT-qPCR, elevated relative gene expression of TLR2 (fold difference, FD = 29.8, p < 0.05), TLR4 (FD = 39.9, p < 0.005), and TLR9 (FD = 10.3, p < 0.005) was observed in pancreatic tumor tissues compared to normal tissues." (PMID 27941651, 2016). "Genetic deletion of TLR9 was similarly ineffective at alleviating pancreatic cancer cachexia in Pan02-challanged animals." (PMID 26172047, 2015). "Others have shown that TLR9 correlates with the invasive and metastatic potential of human pancreatic cancer cell lines." (PMID 26172047, 2015). "ISCOM vaccines that combine TLR9 agonists have been reported to break tolerance in an orthotopic model of pancreatic carcinoma." (PMID 21318177, 2010). "Thus, our results confirm that TLR2- and TLR9-specific intrabodies inhibit pancreatic tumor cell growth." (PMID 38390872, 2024).